MMP1 (matrix metallopeptidase 1)
Diseases named in the same sentence as MMP1 in open-access papers (continued):
Sharing a sentence is not in itself a finding about the gene and the disease.
Hernia (3 papers, 2013 to 2025). "The overexpression of PI16 inhibits MMP activity, and MMPs, including MMP1, MMP2, MMP9, and MMP13, are associated with abdominal hernia development." (PMID 34341761, 2021). "For example, in patients with recurrent hernia there are increased connective tissue levels of MMP-1 and MMP-13 mRNAs and the levels of the corresponding proteins." (PMID 23108733, 2013). "At the molecular level, fibroblasts derived from primary hernia patients show reduced type I:type III procollagen mRNA ratios and heightened MMP-1/-13 expression, consistent with a constitutively degradative phenotype." (PMID 41440470, 2025). "For instance, oxidative exposure markedly increases p38 phosphorylation and downstream MMP-1 and MMP-3 expression in human dermal fibroblasts, leading to ECM disorganization and wrinkle formation—molecular phenomena that closely parallel fascial weakening in hernia pathogenesis." (PMID 41440470, 2025).
inflammatory breast carcinoma (3 papers, 2008 to 2020). An advanced, invasive breast adenocarcinoma characterized by the presence of distinct changes in the overlying skin. "We observed a trend of lower plasma MMP1 levels with increasing tumour size (Odds ratio OR 1.11, p = 0.07) and found significantly lower MMP1 expression in patients with inflammatory breast cancer (OR 0.74, p = 0.02)." (PMID 18366705, 2008). "Furthermore, we observed lower MMP1 levels in plasma from patients with inflammatory breast cancer, a rare but very aggressive disease, and non-inflammatory breast cancer patients with larger tumours." (PMID 18366705, 2008). "The median plasma MMP1 (p = 0.02) and MMP8 (p = 0.007) levels in the non-inflammatory breast cancer patients were almost twice as high as those found in the inflammatory breast cancer patients." (PMID 18366705, 2008).
influenza (3 papers, 2020 to 2025). An acute viral infection of the respiratory tract, occurring in isolated cases, in epidemics, or in pandemics; it is caused by serologically different strains of viruses (influenzaviruses) designated A, B, and C, has a 3-day incubation period, and usually lasts for 3 to 10 days. "The expression of matrix metalloproteinase 1 (MMP1) gene was downregulated in SARS-CoV infection, while MMP1 gene is overexpressed in influenza H7N9, which may lead to deposition of collagen in lungs and consequently gas exchange problem due to fibrosis." (PMID 32754004, 2020).
interstitial lung disease (3 papers, 2015 to 2025). A diverse group of lung diseases that affect the lung parenchyma. "Genetic studies show that polymorphisms in MMP-1 and MMP-3 are linked to distinct clinical phenotypes: for example, the MMP-1 1G/1G genotype correlates with interstitial lung disease, while the MMP-3 5A/5A variant is associated with anti-topoisomerase antibodies." (PMID 41226358, 2025).
intracranial aneurysms (3 papers, 2016 to 2020). "Recent studies have shown that NF-κB p65 can promote inflammatory changes and regulate MMPs (MMP-1, MMP-2, MMP-3, and MMP-9) transcription participating in the initiation and progression of AAA and intracranial aneurysm (IA)." (PMID 26918963, 2016).
invasive ductal carcinoma (3 papers, 2014 to 2017). "Finally, we evaluated Pit-1, MMP-1, and MMP-13 protein expression in 110 human breast invasive ductal carcinomas." (PMID 25527274, 2014).
large cell carcinoma of the lung (3 papers, 2020 to 2022). "MMP1 drives tumour progression in large cell carcinoma of the lung through fibroblast senescence." (PMID 34445346, 2021).
laryngeal carcinoma (3 papers, 2020 to 2024). Carcinoma that arises from the laryngeal epithelium. "In this study, we analyzed the gene expression data of 109 laryngeal cancer samples and screened to obtain three important targets (MMP1, MMP3, and MMP10)." (PMID 32636440, 2020). "Studies have shown that the genetic characteristics of MMP1 may become an independent prognostic factor for laryngeal cancer." (PMID 32636440, 2020). "For example, it has been regularly reported that laryngeal cancer tissues differentially express certain genes, including EMP1, HOXB9, DPY19L2P1, MMP1, and KLHDC7B, representing independent prognosis predictor genes of laryngeal cancer." (PMID 39452555, 2024). "The green module was mapped on the HQ PPI network, and finally, the potential critical targets MMP1, MMP3, and MMP10 for the treatment of laryngeal cancer were obtained." (PMID 32636440, 2020). "And the expression of MMP1 in most of the laryngeal cancer tissues with lymphatic metastasis was higher than that of the laryngeal cancer tissues without lymphatic metastasis." (PMID 32636440, 2020).
lipid metabolism disorders (3 papers, 2024 to 2025). "The reduction and inactivation of STAT3 lead to lipid metabolic disorders and promote triglyceride accumulation by upregulating the mRNA levels of ELOVL7, PPARG, MMP1, MMP13, and TIMP4, and downregulating the mRNA level of PTGS2." (PMID 39125712, 2024).
liver cirrhosis (3 papers, 2013 to 2023). "The previously observed benefits of full-length MMP-1 and MMP-8 delivery into rat models of liver cirrhosis by conventional Ad-vectors provided a standard against which the performance of our Ad-vector-shuttled HBV tMMP8 vector could be compared." (PMID 23301066, 2013).
Lumbar Disc Disease (3 papers, 2008 to 2016). "A polymorphism in the promoter of MMP-1, MMP-2, MMP-3, and MMP-9 genes, which enhance promoter activity, is associated with a higher prevalence of lumbar disc degeneration in Japanese elderly patients and Chinese adult cohorts." (PMID 22394620, 2012).
myopia (3 papers, 2012 to 2025). "In conclusion, our study provides evidence linking inflammation-related gene polymorphisms—particularly in CCL2, TGFβ1, MMP1, and IL1β—to high myopia in children." (PMID 41138034, 2025). "In the case of common myopia there has been one study in a Caucasian cohort that assessed selected SNPs in MMP1, MMP3 and MMP9 and found a positive association of myopia with the rs3025058 in MMP3 (p = 0.015) and the rs17576(R279Q) in MMP9 (p = 0.026)." (PMID 23077567, 2012). "In age- and sex-adjusted allele-based tests, three loci were associated with high myopia: CCL2 rs2857656, TGFβ1 rs2317130, and MMP1 rs2071230 (P = 0.04, 0.03, and 0.04, respectively)." (PMID 41138034, 2025). "Initial findings indicated that the best p values for each trait were 0.02 for myopia at rs2274755 (MMP9), 0.02 for SE at both rs3740938 (MMP8) and rs131451 (MMP11), 0.01 for axial length at rs11225395 (MMP8), 0.01 for anterior chamber depth at rs498186 (MMP1) and 0.02 at rs10488 (MMP1)." (PMID 23077567, 2012).
Oral leukoplakia (3 papers, 2020 to 2025). A thickened white patch on the oral mucosa that cannot be rubbed off. "Furthermore, MMP‐1 was significantly overexpressed in carcinoma of the vocal folds in comparison to leukoplakia and therefore it was associated with disease progression." (PMID 32437034, 2020). "The distribution of MMP-1 levels in 287 patients with leukoplakia (OPMD I, type 1) was similar to that in the HC group, with the same median concentration of 20.9 pg/mL." (PMID 32823758, 2020). "MMP‐1 was expressed in oral leukoplakia as it follows: one tissue sample showed moderate expression (10%), seven patients showed weak expression (70%), and two samples showed no expression of MMP‐1 (20%)." (PMID 32437034, 2020).
Pleural effusion (3 papers, 2015 to 2022). The presence of an excessive amount of fluid in the pleural cavity. "The clinical data in the present study demonstrate the elevated effusion levels of TNF-α, MMP-1 and MMP-9 in TBP and the association of these mediators with amount of pleural effusion and area of pleural fibrosis." (PMID 26367274, 2015).
prostate tumor (3 papers, 2014 to 2023). "Our studies indicated that in prostate epithelial cells over-expressing P4HA1 either MMP1 knockdown or addition of FN-439 significantly reduced MMP1 mediated prostate tumor cell invasion." (PMID 25115393, 2014).
renal cell carcinoma (3 papers, 2009 to 2026). "In vitro overexpression of SLFN5 reduces the motility and invasiveness of malignant human renal cell carcinoma (RCC) cells by negatively regulating the expression of MMP-1 and MMP-13." (PMID 34571887, 2021).
sarcoma (3 papers, 2010 to 2022). A usually aggressive malignant neoplasm of the soft tissue or bone. "Loss of GPR64 in ewing sarcoma cell line leads to decreased PGF and MMP1 expression and reduced cellular growth with induced TRAIL dependent apoptosis." (PMID 31412816, 2019). "The current study extends the understanding of the role of MMP1 in sarcoma biology by localizing the synthesis to tumor cells." (PMID 21170377, 2010). "Subsequent studies demonstrated the correlation of MMP1 silencing by antisense oligonucleotides and shRNA with reduced invasive potential of sarcoma cells in vitro." (PMID 21170377, 2010). "Laser capture microdissection and In Situ hybridization were used to determine cellular origin of MMP1 in human sarcomas." (PMID 21170377, 2010). "LCM and RNA-ISH analysis revealed MMP1 expression was predominantly localized to the tumor cells in all samples of sarcoma (p = 0.05)." (PMID 21170377, 2010). "Messenger RNA In-Situ Hybridization (ISH) was used as an independent means of ascertaining the cellular origin of MMP1 gene expression in human sarcoma tissue." (PMID 21170377, 2010). "Current results support these findings and provide evidence for a pro-metastatic role of MMP1 in a xenogenic murine model of human sarcoma." (PMID 21170377, 2010). "Subsequently, the potential of MMP1 as a therapeutic target in human sarcoma was tested in an orthotopic xenogenic model using shRNA technique to stably silence MMP1 in human sarcoma cells." (PMID 21170377, 2010). "Our finding encouraged us to investigate the role of MMP1 in a xenogenic sarcoma model that appears to be more appropriate model for investigation of the role of MMPs in tumor biology, as there is minimal contribution of MMPs from stromal cells." (PMID 21170377, 2010). "The current study is unique and comprehensive for determining the cellular origin of MMP1 in sarcoma samples, carrying out the stable silencing of target cells and following disease progression in a xenogenic murine model of sarcoma." (PMID 21170377, 2010). "These two complementary lines of evidence indicate that sarcoma cells serve as the primary source of MMP1 in this tumor." (PMID 21170377, 2010). "It demonstrates that MMP1 silencing results in increased local tumor growth and increased vascularity of the primary tumor but less systemic disease burden in a xenogenic murine model of human sarcoma." (PMID 21170377, 2010). "The current report is the first in-depth analysis of role of MMP1 in sarcoma biology." (PMID 21170377, 2010). "The level of GPR64 was higher in ewing sarcoma than other mesenchymal neoplasms, and GPR64 induces placental growth factor (PGF) and metalloproteinase (MMP1) expression." (PMID 31412816, 2019). "The current findings indicating tumor cell production of MMP1 by sarcoma cells is novel and highlights the fundamental differences in MMP biology between carcinomas and sarcomas." (PMID 21170377, 2010). "Hence, it appears that the increase of cell surface CD147 mediated by TRE17 enhances the signaling pathway, which induces the production of MMP1 and MMP9, resulting in increased invasiveness of HT-1080 sarcoma cells." (PMID 35926707, 2022). "Interestingly, both experimental approaches indicate that MMP1 is primarily expressed in human sarcoma cells as and not the surrounding stromal cells." (PMID 21170377, 2010). "Furthermore in the examination of xenogenic metastasis where murine and human MMP1 can be distinguished, it is clear that sarcomas do not induce MMP1 expression in surrounding stromal tissue." (PMID 21170377, 2010).
skin changes (3 papers, 2020 to 2023). "Decreased levels of MMP-1 protein can prevent age-related skin changes by preventing collagen degradation, the fundamental skin element related to the appearance of wrinkles." (PMID 37048555, 2023). "Therefore, increased MMP-1 activity is an important indicator of cellular senescence and age-related skin changes." (PMID 37048555, 2023).
small cell lung carcinoma (3 papers, 2008 to 2021). Small cell lung cancer (SCLC) is a highly aggressive malignant neoplasm, accounting for 10-15% of lung cancer cases, characterized byrapid growth, and early metastasis. "However, stratified analysis by histological types, showed that the MMP1 2G/2G genotype potentially tends to increase the risk of developing small cell lung cancer (adjusted OR = 2.06; 95% CI = 0.94–4.51; P = 0.072)." (PMID 19094243, 2008). "DEGs found to be associated with the small cell lung cancer pathway (ITGA2) and other cancer pathways (MMP1), based on KEGG analysis, were highly expressed in KRAS-mutant AAH." (PMID 34943992, 2021). "GSEA analysis showed that the MMP1, MMP3, and MMP10 high-expression groups participated in tumor-related ECM receptor interaction, small cell lung cancer, and other pathways." (PMID 32636440, 2020).
thrombosis (3 papers, 2016 to 2025). "However, no studies have directly investigated MMP-1 expression in MPNs, and data on the MMP-1 rs1799750 variant association with thrombosis is scarce." (PMID 40724896, 2025). "Specifically, the MMP-1 rs1799750 and MMP-2 rs243865 polymorphisms were significantly associated with an increased risk of venous thrombosis (p = 0.041 and p = 0.022, respectively)." (PMID 40724896, 2025). "In agreement with the role of MMP1 in platelet activation, it was shown in two different in vivo thrombosis models using guinea pigs that inhibition of MMP1 suppressed intravascular thrombus formation and prolonged the time to vessel occlusion." (PMID 33490118, 2020). "Multiple studies have confirmed the role of MMP-1 and MMP-2, along with inflammatory factors, in the pathogenesis of deep vein thrombosis." (PMID 40724896, 2025).
ulcerative colitis (3 papers, 2009 to 2025). An inflammatory bowel disease involving the mucosal surface of the large intestine and rectum. "Fibroblasts from patients with ulcerative colitis also increased MMP-1 while treatment with imipramine resulted in MMP-1-levels with significant inhibition when compared to cells with IL-1β or TNF only." (PMID 19787068, 2009). "We demonstrate that generation of ceramide and activity of acid sphingomyelinase are required for the production of MMP-1, which is believed to damage the colonic mucosa in patients with ulcerative colitis." (PMID 19787068, 2009). "Excessively produced Matrix Metalloproteinase-1 (MMP-1) is believed to damage the colonic mucosa in patients with ulcerative colitis." (PMID 19787068, 2009). "Three of four hub genes identified as NF-κB-regulated in active ulcerative colitis were also regulated in PC-3 MCS in our study (CXCL1, MMP1, and MMP10)." (PMID 40001606, 2025). "This study aims to evaluate the relationship between colonic mucosal and plasma levels of MMP-1 and TIMP-1 with each other and with the severity of ulcerative colitis (UC)." (PMID 19911067, 2009). "In this study, we determined MMP-1 and TIMP-1 expression levels in ulcerative colitis patients compared with normal controls." (PMID 19911067, 2009). "Concentrations of MMP-1 in supernatants of Caco-2-IEC and human intestinal fibroblasts from patients with ulcerative colitis were determined by ELISA." (PMID 19787068, 2009). "In addition, MMP-1 and TIMP-1 expression increased with the severity of ulcerative colitis." (PMID 19911067, 2009). "Induction of MMP-1 by IL-1β or TNF was completely abolished by imipramine in all the investigated primary fibroblasts, including three different sets from healthy control (CO I, CO II, CO III) and three sets from patients with ulcerative colitis (UC I, UC II, UC III)." (PMID 19787068, 2009).
venous ulcer (3 papers, 2021 to 2023). "Lipodermatosclerosis (preceding phase of venous ulcer) is characterized by an increase in mRNA and protein expression for MMP-1 and MMP-2." (PMID 37175078, 2023). "In venous ulcers fluids, MMP-1 and MMP-2 are strongly active." (PMID 37175078, 2023). "Some of the features of advanced stages of CVD, i.e., lipodermatosclerosis and/or venous ulcer, may be linked with increased MMP activity and ECM turnover associated with increased mRNA expression and MMP-1 and MMP-2 protein levels." (PMID 35807509, 2022). "Recently, it was demonstrated that the degree of expression of MMP-1 and MMP-2 evaluated in venous ulcer biopsies, as well as the decrease in their expression along the observation period (4 weeks) represented a predictor of a more successful healing of the venous ulcers evaluated." (PMID 34681353, 2021).
viral hepatitis (3 papers, 2022 to 2023). An acute or chronic inflammation of the liver parenchyma caused by viruses. "On the contrary, other MMPs have a low level of expression such as MMP-1 in viral hepatitis and HCC, and MMP-15 during liver regeneration." (PMID 37509493, 2023).
actinic keratosis (2 papers, 1999 to 2004). A precancerous lesion of the skin composed of atypical keratinocytes. "Although MMP-1, -2, -3 have been detected in actinic keratosis, premalignant and benign tumors were mostly negative for MMP-13 in one study." (PMID 15291964, 2004).
adenomyosis (2 papers, 2013 to 2022). The growth of endometrial tissue inside the muscular wall of the uterine corpus. "MMP-1 2G was also associated with multinodular growth, and it also tended to increase in patients with adenomyosis, suggesting that the 2G (-1607)MMP-1 genotype may be a potential risk marker of myometrial and endometrial hyperplasia." (PMID 24163697, 2013). "Increased MMP1 and MMP13 were detected in the endometrium of women with versus without adenomyosis (P = 0.018 and P = 0.031)." (PMID 35773139, 2022).
alveolitis (2 papers, 2019 to 2025). "Two polymorphisms in the MMP1 and MMP2 genes are associated with the risk of hypersensitivity pneumonitis in the Mexican mestizo population." (PMID 31590404, 2019).
ameloblastoma (2 papers, 2022). The most common odontogenic tumor, arising from the epithelial component of the embryonic tooth and usually affecting the molar-ramus region of the mandible or maxilla. "As in this study, ameloblastoma also expressed MMP-1 and ADAMTS-1, which were highly expressed in our study, suggesting that ADAMTS-1 and MMP-1 could have the same mechanism and may be associated with the behavior of ameloblastoma." (PMID 36338393, 2022). "Several studies also demonstrated that MMPs like MMP-1, MMP-2, MMP-7, MMP-9 and MMP-14 are involved in ECM degradation in the invasion of ameloblastoma [16,21,22,]." (PMID 35243014, 2022).
aortic valve disease (2 papers, 2011 to 2026). "Our results show that elevated pressure induces a gene expression pattern in cells that is considerably similar to that seen in aortic valve disease, in terms of altered expression of ECM proteins (MMP-1, MMP-3) and proinflammatory cytokines (IL-1β, IL-6)." (PMID 21876831, 2011).
brain injuries (2 papers, 2021 to 2022). "A study of traumatic brain injuries suggest MMP-1 and perhaps MMP-10 to be involved in breakdown of BBB and edema formation; however, this warrants further investigation." (PMID 36248130, 2022). "Moreover, CSF MMP-1, -2, -9 and -10 exhibited different dynamics in iNPH compared with patients following traumatic brain injury." (PMID 33985551, 2021).
bronchopulmonary dysplasia (2 papers, 2022 to 2025). Bronchopulmonary dysplasia is a chronic respiratory disease that results from complications related to lung injury during the treatment of infant acute respiratory distress syndrome in low-birth-weight premature infants or from abnormal lung development in older infants. "In a rat model of bronchopulmonary dysplasia (BPD), montelukast treatment inhibited the expression of hyperoxia-induced mesenchymal markers, such as collagen I (Col I), metalloproteinase-1 (MMP-1), MMP-3, TGF-β1, and Smad3, in lung tissues by inactivating the TGF-β1/Smad signaling pathway." (PMID 35517780, 2022).